TNF (tumor necrosis factor)
Diseases named in the same sentence as TNF in open-access papers (continued):
Sharing a sentence is not in itself a finding about the gene and the disease.
colitis (continued). "In addition, anti-TNF antibody hypofucosylation showed that the enhancement of binding to FcγRIIIa generated by this modification can make it more effective against colitis, as it significantly improved the therapeutic outcome." (PMID 35939430, 2022). "To address this, we induced colitis by transferring of naive hTNF-KI T cells into Rag1−/− recipients and modified the microbiota in these mice by vancomycin treatment concomitantly with anti-TNF treatment." (PMID 35383266, 2022). "The sequel of events triggered by TLR-4 activation, including NF-kB and NLRP3 activation, and the release of IL-1β, IL-6, and TNF-α, are considered the most involved in persistent intestinal inflammation triggering and maintenance during colitis, and HIV-1 Tat-induced diarrhea." (PMID 36009057, 2022). "Using a novel humanized model of experimental colitis, we demonstrate that TNF interfered with the tissue repair program via induction of a soluble natural antagonist of IL-22 (IL-22Ra2; IL-22BP) in the colon and abrogated IL-22/STAT3-mediated mucosal repair during colitis." (PMID 35383266, 2022). "Besides, nanostructured lipid carrier-oleuropein was tested in the DSS-induced colitis experimental model and it exhibited a modulation of the inflammatory biomarkers via decreasing the level of TNF-α, IL-6, and hindering neutrophil infiltration." (PMID 35990343, 2022). "In the recovery phase of acute DSS colitis, TNF mediates changes neuronal hyperexcitability." (PMID 35379260, 2022). "Also, G. lucidum ethanol extract administration decreased the expression of inflammatory mediators IL-1β, IL-6, IL-17, and TNF-α in DSS-induced colitis." (PMID 36553765, 2022). "There was an increase in occludin mRNA level in the intestinal perfusion model, suggesting that antisense miR-122a (complexed with lipofectamine) could have the ability to reverse the increased intestinal TJ permeability in TNF-α-induced colitis mice." (PMID 35493445, 2022). "In the Dutch Melanoma Treatment Registry, the survival advantage to irAE was abrogated when anti-TNF is administered for steroid-refractory toxicity, mainly in the context of colitis (median overall survival 17 months in anti-TNF ± steroids versus 27 months in steroids only)." (PMID 35844550, 2022). "Furthermore, the expression of TNF-α and IL-6 in peritoneal macrophages from mice with colitis was down-regulated by a high concentration (10 nM) of PYY 3–36." (PMID 35443853, 2022). "Furthermore, we found that the expression of GPR183 mRNA was increased in patients resistant to TNF blockade therapies compared to responders, and Gpr183 expression was increased in colon tissue in the T cell transfer model of colitis." (PMID 36389671, 2022). "A correlation of DMBT1-/- mice and colitis could be confirmed, in which elevated levels for IL-6 and TNF during inflammation could be seen." (PMID 34989914, 2022). "In our study, T. halophilus suppresses serum IL-1β and TNFα levels in DSS-induced colitis mice." (PMID 35741032, 2022). "It was shown in a trinitrobenzene sulfonic acid (TNBS) and dextran sodium sulfate (DSS)-induced colitis model that overexpression of elafin led to restoration of proteolytic balance; downregulation of IL-6, IL-8, IL-17A, and NFκΒ; and inhibition of TNF-α–induced increased permeability." (PMID 36552023, 2022). "In contrast, it has been reported that IL-26 could protect mice against acute DSS-induced colitis, which is accompanied by reduced expression of TNF, CXCL9, and CXCL10, although its precise role in chronic colitis remains unclear." (PMID 35463017, 2022). "In addition to the colitis models, TNF-α was also shown to be inhibitory in other models of gastrointestinal dysfunction." (PMID 35805922, 2022). "This is accompanied by significantly higher serum levels of IL-6 and TNF-α in mice with colitis." (PMID 34983592, 2022).
colitis (continued). "Inflammatory cytokines (IL-6 and TNF-α) levels were significantly (p < 0.05) increased in the colon tissue of DSS-induced colitis mice when compared with the control group, while LCS-SeNPs significantly reduced (p < 0.05) the levels of pro-inflammatory cytokines IL-6 and TNF." (PMID 36555167, 2022). "Infliximab is an anti-TNF-α antibody that has a significant impact on colitis." (PMID 35756645, 2022). "Similarly, butyrate was less effective in eliciting an anti‐inflammatory response in the TNBS‐induced colitis mouse model, although it induced IL‐10 and reduced IL‐12 and TNF." (PMID 35600637, 2022). "Not surprisingly, it was reported that myricetin could alleviate DSS induced colitis via suppressing the TNF-α/NF-κB pathway, thereby increasing tight junction protein expression compared to colitis mice." (PMID 35805952, 2022). "Therefore, we developed a novel humanized mouse, TNF-driven model of autoimmune colitis that allows studying TNF inhibition by all clinically used anti-hTNF drugs at the stage of fully developed colitis." (PMID 35383266, 2022). "Also, DSS-induced colitis increased systemic inflammation, as demonstrated by increasing IL-6 in serum level and elevated levels of IL-6 and TNF-α levels in cortical tissue, which then results in cortical inflammation." (PMID 35011101, 2022). "In addition, in the colitis model, elevated levels of pro-inflammatory cytokines (TNF-α, IL-1β and IL-6) were found to enhance the inflammatory cascade and cause intestinal tissue damage in UC patients." (PMID 36555167, 2022). "Furthermore, in two mouse models of colitis-associated CRC, PINK1 disruption increased TNFα, IL-1β, IL-6, and IFN-β mRNA expression, and increased colon tumorigenesis, suggesting a role for PINK1 as a tumor inhibitor in CRC." (PMID 36499214, 2022). "It has been documented that the patients of serious colitis could be alleviated by the treatment of anti-TNFα siRNA." (PMID 36064365, 2022). "Our results showed that mebendazole could decrease protein concentrations of these two pro-inflammatory markers in colitis tissue samples, however, only the decrease in TNF-α level was statistically significant." (PMID 35715495, 2022). "TNBS-induced colitis rats showed significantly increased serum levels of TNF-α, IL-2, and IL-6." (PMID 35239781, 2022). "Retrospective data in melanoma, have shown that anti-TNF-α agents do not compromise the efficacy of immune checkpoint inhibitors when administered to combat immune-mediated colitis caused by ICIs15,16." (PMID 36241629, 2022). "Hesperidin could improve colitis by reducing TNF-α, and taurine could slow down the occurrence of many diseases induced by LPS." (PMID 35600958, 2022). "LCS-SeNPs alleviate DSS-induced colitis in mice, probably because of its combined favorable effects, which inhibits pro-inflammatory cytokines (IL-6 and TNF-α) and the production of oxidative index MDA, promotes the production of GSH-Px resulting in the restoration of intestinal permeability." (PMID 36555167, 2022). "Given the complex interaction of microbiota and immune system in the induction of chronic colitis, we hypothesized that microbiota composition may influence TNF expression by colonic cells and subsequent involvement of T-TNF in colitis development." (PMID 35383266, 2022). "To directly address whether IL-22 drives colonic epithelial cell proliferation and subsequent repair during colitis in vivo, we concomitantly neutralized IL-22 by blocking antibodies together with anti-TNF treatment." (PMID 35383266, 2022). "On the other hand, the animal group treated with curcumin nanostructured microemulsion had a significant reduction in the tissue levels of TNF-α (170.5 ± 5.01 pg/mL), as well as IL-1β and IL-6, compared to the colitis treated with NS, and to the COL/MES group rats." (PMID 35976279, 2022).
colitis (continued). "In mice with liver inflammation, TNF played the central role in regulating the expression of maladaptive behaviors and we have also demonstrated a role for TNF in regulating neuronal excitability in rats with colitis induced by trinitrobenzene sulphonic acid." (PMID 35379260, 2022). "Additionally, we found that colitis is associated with meaningfully increase in gene expression of inflammatory cytokines including TLR4, TNF-α and IL-1β." (PMID 35432569, 2022). "From a therapeutic stance, IP in particular has shown potential in a murine model of colitis where administration of the ketoacid not only improved disease outcome, but also decreased expression of pro-inflammatory cytokines, including IL-12, IFNγ, and TNF." (PMID 35052669, 2022). "Altogether, this suggests that TNF produced by T cells drives inflammation during colitis." (PMID 35383266, 2022). "Our results showed that Bp7 and Bp8 intervention obviously reduced the colonic TNF-α and IL-1β levels and significantly elevated the colonic IL-10 levels, indicating that Bp7 or Bp8 effectively relieved the development of inflammation in colitis mice." (PMID 35681301, 2022). "Treatments for colitis include TNF–α antagonist, aminosalicylates, steroids, and immunomodulators." (PMID 35159480, 2022). "These outcomes extend previous studies in which lipid-free apoA-IV reduced inflammation in a mouse model of colitis, inhibited histamine release from basophils in patients with allergic rhinitis and reduced TNF-α secretion from human monocytes following stimulation with lipopolysaccharide." (PMID 35845068, 2022). "Four peptides, DEDTQAMPFR, MLGATSL, SLSFASR, and MSYSAGF, isolated from egg white exerted anti-inflammatory activities in colitis mouse by inhibiting the production of TNF-α and IL-6 as well as reducing the mRNA-expressions TNF-α, IL-6, IL-17, IL-1β, IFN-γ, and MCP-1." (PMID 34234885, 2021). "In addition, probiotic treatment or FMT can reduce the expression and secretion of inflammatory factors (such as IFN-γ, IL-12, TNF-α, IL-6, and IL-1β) to resist colitis by regulating STAT1, STAT4, or NF-κB signals." (PMID 33532501, 2021). "Moreover, we observed enhanced expression of IL-17A, IFNγ and TNFα in colon tissues from the colitis mice (DSS-treated) given the EBV DNA compared to the other groups." (PMID 34210024, 2021). "Similarly, in a DSS-induced experimental colitis model, TNF-α decreases tumor damage by promoting healing through the Wnt/β-catenin signaling pathway." (PMID 34681866, 2021). "However, treatment with C29, DW2009, or donepezil reduced LPS-induced colon shortening, myeloperoxidase activity, and TNF-α and IL-1β expression and increased IL-10 expression in the colon, leading to in the alleviation of colitis." (PMID 34579150, 2021). "Recently, when milk exosomes were fed to DSS (dextran sulfate sodium salt)-induced colitis model mice, the expression of the proinflammatory cytokines IL-6 and TNFα decreased compared with the control group, thereby reducing inflammation and improving necrotizing enteritis." (PMID 34831071, 2021). "The severe reduction of IFN-γ release together with a reduction of other cytokines (e.g. TNF, GM-CSF) upon colitis induction might explain why RptorΔRORγt and RictorΔRORγt mice were partially protected in an α-CD40-mediated colitis model." (PMID 34341503, 2021). "Expression of pro-inflammatory cytokines, including IL-1β, IFN-γ, and TNFα was decreased in colon tissue of EV treated mice compared to DSS-induced colitis mice, whereas expression of the anti-inflammatory cytokines IL-10 and TGFβ were significantly increased in colon tissue of EV treated mice." (PMID 33670708, 2021). "In addition, combination of a P2RX1 inhibitor facilitated the therapeutic efficiency of TNF-α monoclonal antibody (mAb) in mice colitis." (PMID 34354708, 2021). "We wondered whether Exos affect the TNF-α/IκB signaling pathway in LPS-induced colitis; therefore, qRT-PCR and Western blotting experiments were performed." (PMID 34249964, 2021).
colitis (continued). "TNFα may be produced by other leukocytes during colitis, and neutrophils may produce additional factors that contribute to hyperexcitability." (PMID 34511110, 2021). "Both strains exhibited increased responses to TNF and sensitivity to colitis." (PMID 34011076, 2021). "Thus, NAM had anti-inflammatory activity in mice with DSS-induced colitis by inhibiting the proinflammatory cytokines IL-6, IL-12p70, IL-1β, and TNF-α." (PMID 33748287, 2021). "In summary, our data indicate that immunization with the individual recombinant protein of T. spiralis- rTsSp ameliorates the DSS-induced colitis in mice by decreasing the infiltration of macrophages, reducing the production of TNF-α and inducing the expression of IL-10." (PMID 33995396, 2021). "Therefore, we assessed the effect of B-FAHF-2 in vivo using the CD45RBhi T cell transfer model of colitis, which exhibits features like those found in CD including transmural colitis and elevated levels of TNF-α." (PMID 34926527, 2021). "To evaluate whether B. infantis modulates the host genome stability, we employed the DSS-induced colitis model and a TNFα-induced intestinal epithelial cell model." (PMID 34795654, 2021). "Thus, cinacalcet was effective for treating DSS-induced colitis by inhibiting the activation of NF-κB induced by TNFα." (PMID 34880751, 2021). "For example, caffeic acid, tea polyphenols, salvianolic acid, and sesamol could ameliorate colitis by reducing the levels of IL-1β, IL-6, TNF-α, and other pro-inflammatory cytokines in DSS-induced models." (PMID 35059326, 2021). "Moreover, a recent paper showed that PEGylated RA-derived nanoparticles (10, 20 and 30 mg/kg) inhibited TNF-α production dose-dependently in DSS-induced colitis." (PMID 33530569, 2021). "In addition, blocking TNF-α with infliximab, after tapering of glucocorticoid therapy, also reduced colitis in cancer patients treated with different ICI inhibitors without affecting their efficacy." (PMID 33777008, 2021). "Similarly, in male Balb/c mice, supplementation with stevoside, at either high (100 mg/kg BW) or low (50 mg/kg BW) dose for 7 days prior to DSS colitis induction significantly lowered colonic TNFα levels and attenuated the NF-κB and MAPK signaling pathways." (PMID 34631773, 2021). "Again, colitis induction depended on the presence of microbiota and TNFα/IFNγ signaling." (PMID 34188111, 2021). "TNF-α, IL-6, and IL-1β are the most important cytokines involved in the pathogenesis of colitis." (PMID 33854556, 2021). "However, oral gavage and intraperitoneal injection of buspirone alleviated IS-induced colitis: it suppressed myeloperoxidase activity, IL-1β, IL-6, and TNF-α expression, and NF-κB+/CD11c+ cell population in the colon." (PMID 33731795, 2021). "The colitis model cells were induced with TNF-α and then treated with Xi Lei San and alum crystals." (PMID 33967625, 2021). "The British Association of Dermatologists recommends the use of TNF-α inhibitors on a case-by-case basis in pregnancy, and the European Crohn’s and Colitis Organization has found that TNF-α inhibitors may be used safely until the third trimester." (PMID 35096797, 2021). "Furthermore, Clostridium tyrobutyricum was shown to suppress colonic TNF-α expression in murine dextran sulfate sodium (DSS)-induced colitis." (PMID 34206478, 2021). "To assess whether the inhibitory effect of ZS40 on colitis was mediated by the NF-κB pathway, we measured the relative expression of IκB-α, NF-κBp65, IL-6, and TNF-α mRNA and protein in colon tissues." (PMID 34867317, 2021). "Notably, B. infantis administration decreased DSB levels in both DSS-induced colitis and TNF-treated colonial cell model." (PMID 34795654, 2021). "We accordingly observed a reduction in the levels of TNFα in the animals treated with the L. lactis-SlpB, where the L. lactis NCDO 2118 wild-type strain failed to prevent the increase in cytokine secretion caused by DSS-induced colitis." (PMID 34987390, 2021).
colitis (continued). "Compared with the sham group, colonic pro-inflammatory cytokines, including TNF-α, IL-1β, and IL-8, were significantly increased in the colitis group, and these changes could be significantly reversed by 20 and 80 mg/kg aucuboside." (PMID 34335262, 2021). "Glucocorticoids-refractory patients, and patients with recurrent colitis may require the TNF-α inhibitor infliximab, which typically resolves inflammation within 1–3 doses and often with a single dose." (PMID 33407605, 2021). "We further demonstrated that administration of the rTsSp without the additional adjuvant before the induction of DSS-induced colitis reduced the severity of intestinal inflammation and the disease index; it suppressed macrophage infiltration, reduced TNF-α secretion, and induced IL-10 expression." (PMID 33995396, 2021). "In addition to TNFα, an increase of another pro-inflammatory marker was observed in the experimental groups treated with colitis." (PMID 33499240, 2021). "In our study, TNF-α-induced CACO2 cells were used as an in vitro model of colitis." (PMID 33967625, 2021). "In contrast to other murine colitis models, the herein used S.Tm infection model follows precise and reproducible kinetics, which can help resolve TNF-dependent and independent effects on the mucosa during the stage-wise progression of gut inflammatory disease." (PMID 33731826, 2021). "Mice were intraperitoneally injected with AOM (10 mg/kg) on day -7, followed by three cycles of drinking 2.5% DSS-containing water for 5 days with an interval of 14 days to determine the dynamical changes in the levels of both forms of TNF-α during the transformation from colitis to tumors." (PMID 34675913, 2021). "In the colitis patient, TNF-α and IL-1β not only increase the infiltration of neutrophils, but also cause damage to the intestinal barrier, which may induce diarrhea symptoms in patients." (PMID 34199820, 2021). "Beta-sitosterol was found to markedly reduce weight loss, colonic length shortening, and microscopic changes in DSS-induced colitis and to reduce TNF-α, IL-6, and IL-1β levels in the intestinal tissues of experimental colitis mice in a concentration-dependent manner." (PMID 34149863, 2021). "While the colitis-associated increase in serum tumor necrosis factor α (TNFα) levels was not exacerbated among genotypes, serum interleukin 6 (IL-6) levels were significantly increased in Usp22fl/fl animals undergoing acute colitis." (PMID 33920268, 2021). "Anti-TNF-α was preferred as the immunomodulatory agent in most colitis cases (21/22) and treatment benefit was observed in 20/21 cases; one patient with grade 3 colitis was treated with first-line anti-TNF-α as a steroid-sparing option with toxicity resolution." (PMID 34208218, 2021). "The small RNAs contained in ginger ELNs had protective effects against DSS-induced colitis by reducing the levels of pro-inflammatory cytokines, such as IL-1β and TNF-α, and by promoting the expression of interleukin 22 (IL-22) through I3A, which activates the aryl hydrocarbon receptor pathway." (PMID 34065193, 2021). "Inflammatory response plays a key role in the activation of IL-6, IL-1β, and TNF-α in colitis." (PMID 35059326, 2021). "Finally, we found that a specific P2RX1 inhibitor succeeded to improve the therapeutic efficiency of anti-TNF-α therapy in DSS-induced mice colitis." (PMID 34354708, 2021). "There are reports that treatment with NLRP3 inhibitors can relieve colitis under DSS exposure, which might be caused by the local reduction of pro-inflammatory cytokines, including IL-1β, TNF-α, and IFN-γ." (PMID 34955826, 2021). "Extracellular vesicles (1 × 109 particles/mL) also inhibited TNFα-induced colitis." (PMID 34745425, 2021). "Similarly, the injection of IGNVs loaded with curcumin (IGNVs-Cur), a known anti-inflammatory agent, increased the survival rate of mice with DSS-induced colitis and decreased TNF-α, IL-6, and IL-1β levels in colonic tissue compared with free Cur and GNVs-Cur." (PMID 34065193, 2021).